GIP (gastric inhibitory polypeptide)
Diseases named in the same sentence as GIP in open-access papers (continued):
Sharing a sentence is not in itself a finding about the gene and the disease.
Insulin resistance (continued). "Furthermore, it has been suggested that GIP plays a role not only as an incretin hormone but also as a regulator of inflammation and insulin resistance." (PMID 32090124, 2020). "In the present study, we investigated the effect of GIP on age-related body weight gain and insulin resistance using GIP-knockout homozygous (GIP−/−) and heterozygous (GIP+/−) mice, which have entirely absent and 50% reduced GIP secretion compared to wild-type (WT) mice, respectively." (PMID 31977316, 2020). "Increased postprandial GIP secretion positively correlates with insulin resistance, and chronic local and systemic inflammation, which may involve IL-6 signaling." (PMID 32069846, 2020). "Eriodictyol supplementation in mice fed with a high-fat diet for 16 weeks improved insulin resistance by suppressing hepatic gluconeogenesis, enhancing glucose utilization, and modulating the production and release of gastric inhibitory polypeptide and glucagon-like peptide-1." (PMID 32781523, 2020). "It suggests that lower postprandial GIP levels may prevent enhanced glucagon secretion in the early stage of insulin resistance." (PMID 32411223, 2020). "Furthermore, a decrease in GIP secretion drives to adipocyte hypertrophy arrest and insulin resistance amelioration." (PMID 31261732, 2019). "Again, the positive linear correlations found between CCK and IL-1, IL-1, and GIP, and GIP and insulin (other anorexigen) may perpetuate the anorexia and the insulin resistance suffered by our patients." (PMID 31191339, 2019). "Thus, it presumably reflects alleviation of glucotoxicity, or the actions of GIP to improve insulin resistance." (PMID 28004148, 2017). "Gastric cancer surgery led to decreased ghrelin and leptin and increased PYY and GIP, which might have a role in improving insulin resistance and glucose homeostasis." (PMID 29216250, 2017). "After gastric cancer surgery, ghrelin and leptin levels were decreased and PYY and GIP levels were increased, which may have a role in improving insulin resistance." (PMID 29216250, 2017). "Low secretion characteristics of GIP may contribute to the suppression of adipocyte hypertrophy and insulin resistance." (PMID 28166771, 2017). "The synthesis and secretion of GLP-1 and GIP were decreased in the presense of Insulin resistance." (PMID 28893239, 2017). "Ageing is associated with insulin resistance and impaired glucose tolerance which may be influenced by changes in small intestinal hormone (GLP-1, GIP) secretion." (PMID 26751475, 2016). "We may therefore deduce that GIP mRNA reduction in the intestine exposed to systemic insulin resistance corroborates GIP signaling defects in insulin-resistant and T2D subjects." (PMID 26376914, 2015). "In addition to the observed reduction of the GIP expression in presence of insulin resistance, three other intestinal peptides are differentially regulated." (PMID 26376914, 2015). "These combined observations suggest that GLP-1 and GIP produced largely by islet alpha cells may play a hitherto unproven role in islet adaptation to insulin resistance and the control of glucose homeostasis." (PMID 24967820, 2014). "Additionally, a potential role of GIP on adipose tissue insulin resistance mediated by osteopontin regulation has also been suggested." (PMID 23298335, 2013). "However, unlike GLP1, insights from rodent-based models reveal that the direct effects of GIP may be less desirable metabolically, including the mediation of energy intake and markers of insulin resistance in response to carbohydrate ingestion." (PMID 40431453, 2025). "Thus, GIP sensitivity in WAT may diminish under conditions of insulin resistance or hyperglycemia, leading to impaired fat metabolism." (PMID 38579777, 2024).
Insulin resistance (continued). "Treatment of obese mice with GIP receptor (GIPR) antagonist leads to rapid improvement in β‐cell function and glucose tolerance through alleviation of insulin resistance, but it remains to be investigated whether the effects of blocking GIP in humans are similar to those observed in mice." (PMID 37442561, 2023). "Furthermore, Lactococcus lactis lowered the respiratory exchanges ratio, increased night cycle activity, increased serum gastric inhibitory polypeptide (GIP) which stimulates insulin production, and lowered resistin, the adipose tissue hormone that is a biomarker of insulin resistance." (PMID 37763997, 2023). "However, the effect of age-related GIP hypersecretion on body weight and fat mass gain, and insulin resistance remains unclear." (PMID 31977316, 2020). "The patients of acromegaly with normal glucose tolerance could maintain euglycaemia even in the face of significantly increased insulin resistance due to the stimulatory/cytotrophic effect of elevated GIP and GH/IGF-1 on β-cells and/or as a part of innate β-cell reserve." (PMID 30948746, 2019). "Down-regulation of GIP expression may suggest reduced mRNA expression levels or may alternatively indicate a decrease in the number of K-cells in the duodenum in presence of systemic insulin resistance." (PMID 26376914, 2015). "GIP infusion might exacerbate insulin resistance in the diabetic mice by increasing adiposity." (PMID 22536426, 2012). "Finally, although only limited data is present, plasma GIP levels may important as seen from in vitro studies showing a GIP induced reduction in insulin resistance in 3T3-L1 adipocytes through activation of Akt." (PMID 21276223, 2011). "Dynamic changes in serum GIP, GLP-1, insulin, and insulin resistance between 1 and 4 weeks after PBM, measured using HOMA-IR, were identified for the evaluation of underlying mechanisms on altered gut microbiome over 1–4 weeks in the D-LED PBM group." (PMID 36359885, 2022). "Bioactive peptides also activate the release of incretin hormones including GIP and GLP-1 which have an important role in improvement of insulin resistance." (PMID 32958070, 2020). "In addition, ED improved insulin resistance (IR) by suppressing hepatic gluconeogenesis, enhancing glucose utilization, and modulating the production and release of two incretin hormones, namely gastric inhibitory polypeptide (GIP) and glucagon-like peptide-1 (GLP-1)." (PMID 30862092, 2019). "Some phytomolecules may additionally alleviate insulin resistance and stimulate incretin (GLP-1/GIP) secretion, potentially enhancing their neuroprotective." (PMID 41971071, 2026). "The insulin resistance-attenuating effect of LASSBio-2129 can be generated through daily glycemic control by inhibiting the DPP-4 enzyme, which is known to prolong the half-life of GLP-1 and GIP, thereby corroborating the effect observed in this study." (PMID 41155701, 2025). "Notably, GLP-1 receptor agonists, as well as dual GLP-1/GIP and GLP-1/glucagon receptor agonists, appear to exert the most comprehensive effects on MASLD, simultaneously improving steatosis, insulin resistance, inflammation, and body weight." (PMID 40650294, 2025). "In obese children, the release of GIP and GLP-1 may be altered, contributing to insulin resistance and hyperinsulinemia." (PMID 40649920, 2025). "One of the main highlighted mechanisms of hypothalamic inflammation, caused by a high-calorie, high-fat diet, is the increase in the intestinal hormone glucose-dependent insulinotropic polypeptide (GIP), which promotes hypothalamic inflammation and insulin resistance." (PMID 40141399, 2025). "Similarly, the IAPPO-IgA levels correlated positively with the metabolic markers glucose, glucagon, and GIP, as well as with inflammatory total IgA, CRP, and GGT, and the change in IAPPO-IgA levels correlated positively with the change in insulin resistance." (PMID 39062913, 2024).
Insulin resistance (continued). "Therefore, drugs that are DPP-4 inhibitors delay the breakdown of endogenous incretins GIP and GLP-1 and are successfully used to combat insulin-resistance and DM 2 management." (PMID 35205155, 2022). "For instance, ghrelin and gastric inhibitory polypeptide (GIP) may affect fat oxidation and thereby a protective role in lipid-induced skeletal muscle insulin resistance." (PMID 34220709, 2021). "Our study postulates that elevations in basal GIP levels during pregnancy in GDM subgroups may play an effective role in controlling fasting glycaemia and insulin resistance." (PMID 32090124, 2020). "In the present study, the effects of absent and reduced GIP secretion on age-related fat mass gain and insulin resistance under normal fat diet feeding condition were investigated using the same GIP-knockout mouse used in the previous study." (PMID 31977316, 2020). "It has been shown that in obese individuals, insulin resistance reduces gastric inhibitory polypeptide receptor expression and GIP activity in subcutaneous adipose tissue but not in visceral adipose tissue." (PMID 31477157, 2019). "The magnitude of insulin resistance induced by chronic GH exposure is independent of the glycaemic status and emergence of hyperglycaemia is an outcome of “β-cell dysfunction”, GIP resistance and hyperglucagonemia." (PMID 30948746, 2019). "Role of GLP-1 and GIP in beta cell compensatory responses to beta cell attack and insulin resistance were examined in C57BL/6 mice lacking functional receptors for GLP-1 and GIP." (PMID 24967820, 2014). "In contrast, hydrocortisone treatment and induction of insulin resistance increased islet numbers and area, with enhanced beta cell replication, elevated mass of beta and alpha cells, together with co-expression of GLP-1 and GIP with glucagon in islets." (PMID 24967820, 2014). "Although OP rats did not develop insulin resistance, the lowering of plasma GIP by all dietary levels of RS was considerable and deserves further investigation in animal models with impaired insulin sensitivity." (PMID 23098187, 2012). "In addition to reduction in insulin resistance, bariatric surgery is known to increase incretins like glucagon-like peptide-1 (GLP-1) and glucose-dependent insulinotropic polypeptide (GIP), which lead to improved beta-cell function." (PMID 22384240, 2012). "Additionally, bioactive peptides activate the release of incretin hormones (gastric inhibitory polypeptide and GLP-1), which improve insulin resistance and inhibit dipeptidyl peptidase-IV, consequently reducing the degradation of gastric inhibitory polypeptide and GLP-1." (PMID 37511996, 2023). "In addition, insulin resistance in obese individuals results from improperly low secretion and increased degradation of incretin hormones, such as GLP-1 (glucagon-like peptide 1) and GIP (gastric inhibitory polypeptide)." (PMID 37445466, 2023). "While the effect of IL-1RA was partially mediated through BMI, the effect of GIP was not, suggesting that circulating GIP levels could be explored further as a potential biomarker for the development of insulin resistance." (PMID 38049854, 2023). "Therefore, it is important to accumulate evidence for the roles of GIP signaling in Asian people who are generally prone to have reduced β‐cell function rather than increased insulin resistance." (PMID 35452190, 2022). "Similarly, glucose-stimulation of insulin, but not GIP, secretion was elevated in pregnancy, helping to maintain normal glucose tolerance despite coexistent insulin resistance." (PMID 24236022, 2013). "However, insulin resistance is also related to dysfunction in a broader, integrated network of metabolic hormones beyond insulin, including peptide tyrosine tyrosine (PYY), glucagon like peptide-1 (GLP-1), and glucose-dependent insulinotropic polypeptide (GIP)." (PMID 33328877, 2020).
Insulin resistance (continued). "Hence, in the setting of insulin resistance, it can therefore not be concluded whether a GPR119-mediated increase in GIP levels is causing the rise in glucagon after the current meal challenge." (PMID 23781322, 2013). "This comparative study on clinical effects has some limitations that include lack of data collection on insulin resistance alleviation degree and lack of gastrointestinal GLP-1, GIP, and PYY hormones data collection." (PMID 26198306, 2015).
Hyperglycemia (103 papers, 2011 to 2026). An increased concentration of glucose in the blood. "This research theorized that hyperglycemia can lead to a downregulation of GIPr causing decreased GIP response despite therapeutic or even supratherapeutic levels of GIP." (PMID 37526853, 2023). "The hyperglycaemia results from beta-cell dysfunction and is associated with lower fasting and stimulated gastric inhibitory polypeptide (GIP) levels." (PMID 29026101, 2017). "Compared with enteral nutrition (EN), patients treated with parenteral nutrition (PN) are more likely to have significant hyperglycemia because PN bypasses glucagon-like peptide-1 and gastric inhibitory polypeptide in the gastrointestinal tract, resulting in the loss of the incretin effect." (PMID 40692592, 2025). "While hyperglycaemia may possibly be an important modulator, the possibility that the response to GIP is caused by critical illness per se cannot be excluded." (PMID 25613747, 2015). "The objectives of this study were to determine the acute effects of exogenous GIP (4 pmol/kg/minute) on glycaemia, gastric emptying, glucose absorption, and insulin secretion during enteral nutrition in patients with acute critical illness-associated hyperglycaemia." (PMID 25613747, 2015). "Given that GIP-mediated insulinotropic effects are diminished under chronic hyperglycemia, the biased agonism of tirzepatide toward the GLP-1 receptor plays a crucial role in its efficacy." (PMID 40607140, 2025). "The expression of Gipr is subject to differential splicing in the β-cells under conditions of hyperglycemia, ultimately influencing GIP sensitivity in diet-induced obese (DIO) mice." (PMID 40024571, 2025). "Several preclinical studies show that the impaired insulinotropic action of GIP under conditions of hyperglycemia is paralleled by decreased expression of the GIP receptor (Gipr) in pancreatic islets." (PMID 40024571, 2025). "Once chronic hyperglycemia is corrected, GIP-mediated insulin secretion is restored, allowing tirzepatide to enhance insulin secretion through both the GIP and GLP-1 receptors." (PMID 40607140, 2025). "GLP-1 synergizes with GIP to promote metabolic homeostasis, prevent hyperglycemia and hypoglycemia, attenuate dyslipidemia, and reduce the risk of cardiovascular disease in patients with T2DM and obesity." (PMID 39598478, 2024). "The pathophysiology of pasireotide-induced hyperglycemia involves decreased secretion of the incretin hormones GIP (glucose-dependent insulinotropic polypeptide) and GLP-1 (glucagon-like peptide-1)." (PMID 38405148, 2024). "Despite GIP’s suggested role in insulin sensitivity in healthy individuals, GIP resistance has been observed in a T2D state when hyperglycaemia reduces GIP receptor expression in β-cells." (PMID 38049854, 2023). "In Covid-19, GIP response to the meal is impaired, leading to postprandial hyperglycemia and abnormal glucose homeostasis." (PMID 37208555, 2023). "Although hyperglycaemia can severely impair GIP’s insulinotropic effects, these can be restored by using GLP-1’s preserved insulinotropic and glucagonostatic effects to normalize blood sugar." (PMID 37900147, 2023). "Similar to GLP-1, a 42-amino acid glucose-dependent insulinotropic polypeptide (GIP) has insulinotropic effects and lowers hyperglycemia." (PMID 35383532, 2022). "This study was aimed to determine the therapeutic effects and potent mechanisms of a novel GLP-1/GIP dual agonist on hyperglycemia and myocardial injury in diabetic mice." (PMID 35383532, 2022). "This study was aimed to evaluate the therapeutic effects and potent mechanisms of a novel GLP-1/GIP dual agonist on hyperglycemia and myocardial injury in diabetic mice." (PMID 35383532, 2022). "Compared to GLP-1, which suppresses glucagon secretion during hyperglycemia, GIP can stimulate glucagon secretion during low and high glycemia." (PMID 36289848, 2022).
Hyperglycemia (continued). "Administration of the protein preload markedly reduced postprandial hyperglycemia and increased plasma GIP and insulin levels whereas increased GLP-1 secretion after the carbohydrate meal." (PMID 33419065, 2021). "After surgery, indices of IS improved, GIP and glucagon levels decreased significantly in both the groups, while there was no significant change in indices of β-cell function in those with hyperglycaemia." (PMID 30948746, 2019). "In contrast, the indices of β-cell function were significantly lower in patients of acromegaly with hyperglycaemia, despite significantly higher GIP levels, with comparable IR indices and GH/IGF-1 levels." (PMID 30948746, 2019). "The fasting GIP levels and its AUC were higher in those with hyperglycaemia than in those with euglycaemia." (PMID 30948746, 2019). "The indices of β-cell function however are significantly lower only in those with hyperglycaemia despite higher GIP levels." (PMID 30948746, 2019). "DPP-4 inhibitors significantly increased the GLP-1 and GIP levels, reduced the glucagon levels during hyperglycemia, and sustained glucagon counterregulation during hypoglycemia in patients with T1DM." (PMID 29507862, 2018). "In separate animals, islets were perfused ex vivo with GIP (10−6–10−12 mol/L) during normo‐ and hyperglycemia and arteriolar responsiveness was recorded." (PMID 29673130, 2018). "In conclusion, we have shown that it is hard for trehalose to give rise to hyperglycemia and hypersecretions of insulin and GIP following ingestion." (PMID 28166771, 2017). "At hyperglycaemia GIP indeed stimulates insulin release, but in the presence of euglycaemia or hypoglycaemia GIP stimulates glucagon secretion." (PMID 26859145, 2016). "For this reason there is considerable interest in the potential use of GLP-1 and GIP in the management of hyperglycaemia in the critically ill patient." (PMID 25613747, 2015). "Chronic hyperglycaemia has been shown to profoundly diminish the insulinotropic effect of GIP; that is, the insulinotropic effect is almost abolished in patients with longstanding hyperglycaemia." (PMID 25613747, 2015). "Among these, glucagon-like peptide 1 (GLP1) and glucose-dependent insulinotropic polypeptide (GIP) play a central role in dampening postprandial hyperglycemia after carbohydrate ingestion." (PMID 25486965, 2015). "The GIP infusion worsened the hyperglycemia in Apoe−/− mice, but atherosclerosis in these animals was milder and less developed." (PMID 22536426, 2012). "Infusion of GIP during a mixed meal further increases circulating levels of glucagon in people with T2D, and this coincides with a greater glucose excursion and thus postprandial hyperglycemia." (PMID 40024571, 2025). "In summary, the decreased incretin effect in patients with T2D is attributed mainly to an impaired insulinotropic action of GIP, potentially because of impaired β-cell function and down-regulation, degradation or alternative splicing of the GIP receptor under conditions of hyperglycemia." (PMID 40024571, 2025). "Moreover, the mechanism of action of tirzepatide, a dual GIP and GLP-1 RA recently approved for use in patients with T2DM, indicates its high potential in the treatment of pasireotide-associated hyperglycemia." (PMID 39735646, 2024). "In humans, GIP may inhibit bone resorption during intravenous infusion, and the antiresorptive effect appears to be more pronounced during hyperglycemia." (PMID 38725663, 2024). "The combined effect of GLP-1 and GIP in stimulating insulin secretion in a glucose-dependent manner, prolonging stomach emptying time, and suppressing hunger, thus, significantly improving the management of postprandial hyperglycaemia in particular." (PMID 37133312, 2023).